LINC00365 (long independently transcribed non-coding RNA 365)
Gene: Long non-coding RNA gene on chromosome 13 (30,099,909 to 30,108,934, reverse strand). Ensembl gene ENSG00000224511.
Diseases named in the same sentence as LINC00365 in open-access papers:
LINC00365 is named in the same sentence as 3 diseases in open-access papers, as found by Europe PMC text mining. Sharing a sentence is not in itself a finding about the gene and the disease. The quoted sentences say what the papers report.
colorectal cancer (2 papers, 2020 to 2024). A primary or metastatic malignant neoplasm that affects the colon or rectum. "We previously reported that LINC00365 expression in colorectal cancer is closely associated with poor patient outcomes." (PMID 39439418, 2024). "In summary, our study revealed that LINC00365 is highly expressed in colorectal cancer tissues and promotes cell migration and invasion." (PMID 39439418, 2024). "In this study, we aimed to further explore the role of LINC00365 in colorectal cancer and tentatively address its potential molecular mechanisms." (PMID 39439418, 2024). "Our previous work demonstrated that LINC00365 is upregulated in colorectal cancer and promotes cell proliferation and invasion." (PMID 39439418, 2024). "Our findings suggest that LINC00365 may serve as a molecular biomarker for estimating the prognosis of patients with colorectal cancer and as a potential therapeutic target for colorectal cancer." (PMID 39439418, 2024). "LINC00365 is upregulated in colorectal cancer specimens, and it may be involved in the process of CRC cells by mediating the Wnt/β-catenin pathway." (PMID 33381546, 2020).
cancer (1 paper, 2020). A tumor composed of atypical neoplastic, often pleomorphic cells that invade other tissues. "However, the expression of LINC00365 was downregulated in our study, which may be caused by different cancer types." (PMID 33381546, 2020).
tumor (1 paper, 2024). "Our further observations revealed that the knockdown ofLINC00365 significantly weakened the proliferation of tumor cells and generated more pyroptotic bodies, which suggests that LINC00365 is potentially associated with the pyroptosis of CRC cells." (PMID 39439418, 2024). "Nude mouse xenograft experiments further verified that LINC00365 can regulate tumor growthin vivo." (PMID 39439418, 2024).